FTO (FTO alpha-ketoglutarate dependent dioxygenase)
Diseases named in the same sentence as FTO in open-access papers (continued):
Sharing a sentence is not in itself a finding about the gene and the disease.
osteosarcoma (13 papers, 2021 to 2025). A usually aggressive malignant bone-forming mesenchymal neoplasm, predominantly affecting adolescents and young adults. "Multivariate Cox-regression analysis identified METTL3, YTHDC1, and FTO as significant osteosarcoma OS probability-associated markers in training set." (PMID 34011074, 2021). "Moreover, Kaplan–Meier survival analysis showed that low FTO expression was associated with shorter overall survival in osteosarcoma patients." (PMID 41145484, 2025). "For example, in osteosarcoma, FTO demethylates m6A modifications, reducing the stability of DACT1 mRNA, thereby decreasing DACT1 expression and subsequently activating the Wnt signaling pathway." (PMID 39849461, 2025). "For example, in-vitro cell experiments in previous studies have demonstrated that FTO inhibits apoptosis in osteosarcoma cells and myoblasts." (PMID 40181982, 2025). "The results of cell immunofluorescence showed that TRIM17 and FTO were co-localized in osteosarcoma cells." (PMID 41145484, 2025). "To further investigate the role of the FTO gene in osteosarcoma, we performed RNA-seq analysis on the control cell line (siNC) and the FTO knockdown cell line (si-FTO) in 143B cells." (PMID 41145484, 2025). "In the article “MiR-150-5p inhibits cell proliferation and metastasis by targeting FTO in osteosarcoma” (Oncology Research." (PMID 40612875, 2025). "Through analyzing the prognosis information of osteosarcoma patients, METTL3, YTHDC1, and FTO were identified as significant markers associated with OS probability." (PMID 34011074, 2021). "To determine whether FTO also functions as a demethylase in osteosarcoma progression, we performed RNA-seq and MeRIP-Seq analyses in the FTO knockdown group and the control group." (PMID 41145484, 2025). "In summary, TRIM17 can interact with FTO, and FTO may regulate the function of TRIM17 in osteosarcoma by influencing the activation of the AKT-mTOR signaling pathway." (PMID 41145484, 2025). "Therefore, we selected two m6A methylation regulators (FTO and IGF2BP2) using univariate Cox proportional risk regression model to explore their prognostic value in osteosarcoma and establish gene signature." (PMID 33952279, 2021). "METTL3, YTHDC1, and FTO were identified as key regulators, and the osteosarcoma prognostic signature based on these m6A regulator could prognostically stratify the patients independently of potential confounding factors." (PMID 34011074, 2021). "Among the m6A methylation regulators, the abnormal expression of FTO and IGF2BP2 was found to be significantly associated with the progression of osteosarcoma and is considered to be the key factors that can independently predict the prognosis of patients with osteosarcoma." (PMID 33952279, 2021). "However, in osteosarcoma, we found that FTO is a protective gene, and high FTO expression promotes survival in patients with osteosarcoma." (PMID 33952279, 2021). "Our data showed that FTO might play a tumor suppressor gene role in osteosarcoma." (PMID 33952279, 2021). "In conclusion, TRIM17 promotes FTO degradation via ubiquitination, a post-translational modification, and positively modulates the AKT/mTOR signaling pathway, thereby enhancing osteosarcoma malignancy." (PMID 41145484, 2025). "As an E3 ubiquitin ligase, TRIM17 promotes FTO ubiquitination and degradation, thereby activating the AKT/mTOR pathway to drive osteosarcoma progression." (PMID 41145484, 2025). "Mechanistically, TRIM17 regulates FTO degradation via ubiquitination, modulates PDK1 gene methylation, and thereby activates the AKT/mTOR signaling pathway, promoting osteosarcoma malignancy." (PMID 41145484, 2025). "In conclusion, in vivo assays revealed that TRIM17 positively regulates the activation of the AKT/mTOR signaling pathway via FTO-mediated PDK1 expression, thereby enhancing osteosarcoma growth." (PMID 41145484, 2025).
osteosarcoma (continued). "In the progression of osteosarcoma, the expression of DACT1 is regulated by the FTO-mediated m6A methylation modification." (PMID 40356725, 2025). "In vitro rescue assays revealed that FTO overexpression partially reversed TRIM17-induced activation of the AKT/mTOR signaling pathway and attenuated osteosarcoma malignancy." (PMID 41145484, 2025). "The m6A demethylase FTO mediates mRNA demethylation, promoting the decay of KLF3 mRNA and decreasing its expression, consequently facilitating osteosarcoma proliferation and metastasis." (PMID 37197432, 2023). "Recent studies suggest that FTO may activate the AKT pathway by regulating the m6A modification of PDK1, but whether this mechanism is conconservative in osteosarcoma still needs to be verified." (PMID 41145484, 2025). "Also, the destabilizing effects of FTO on DACT1 mRNA promotes Wnt signaling and consequently osteosarcoma metastasis." (PMID 37197432, 2023). "Mechanistically, TRIM17 promotes the ubiquitination and degradation of FTO protein, enhances PDK1 mRNA stability via N6-methyladenosine (m6A) modification, and subsequently promotes phosphorylation-dependent activation of the AKT/mTOR signaling pathway, thereby driving osteosarcoma malignancy." (PMID 41145484, 2025). "In conclusion, TRIM17 regulates FTO expression by promoting post-translational ubiquitination modification of FTO protein, thereby positively modulating the AKT/mTOR signaling pathway to enhance the clonability and survival potential, migration, and invasion of osteosarcoma." (PMID 41145484, 2025). "Therefore, our assayal results suggest that TRIM17 regulates the expression of PDK1 through FTO-mediated m6A demethylation in osteosarcoma, and further activates downstream AKT/mTOR signaling pathway activity to positively regulate the malignancy of osteosarcoma." (PMID 41145484, 2025). "Moreover, there was a significant decrease in demethylase ALKBH5 mRNA inversely correlated with m6A contents in all three osteosarcoma cell lines as compared with hOB cells, but not in METTL3, METTL14, WTAP, and FTO." (PMID 33431791, 2021). "To our knowledge, we are the first to report that osteosarcoma patients could be prognostically stratified using METTL3, YTHDC1, and FTO, which is independent of potential confounding factors including age, gender, and metastatic status." (PMID 34011074, 2021).
papillary thyroid cancer (13 papers, 2021 to 2025). "Correlation between fat mass and obesity-associated protein (FTO) expression and the clinicopathological features of papillary thyroid carcinoma." (PMID 35721711, 2022). "A few researches evaluated the association of polymorphisms at SERPINA5 and fat mass and obesity-associated protein (FTO) genes with papillary thyroid cancer (PTC) globally." (PMID 34837923, 2021). "Nonetheless, Zhao's research indicated that the FTO rs8050136 polymorphism might be linked to thyroid papillary carcinoma." (PMID 40391584, 2025). "It is reported that FTO inhibited glycolytic metabolism in papillary thyroid cancer thereby abrogating tumor growth." (PMID 41426311, 2025). "FTO is able to inhibit the occurrence of papillary thyroid carcinoma by downregulating SLC7A11 in m6A independently." (PMID 38200441, 2024). "In papillary thyroid cancer, FTO acts as a tumor suppressor via suppress glycolysis and cell growth through IGF2BP2-mediated m6A modification." (PMID 36765416, 2023). "Another study suggested that FTO suppressed glycolysis and growth of papillary thyroid cancer via decreasing stability of APOE mRNA in an m6A dependent manner." (PMID 37840133, 2023). "However, in papillary thyroid cancer, FTO acts as a tumor suppressor to inhibit APOE expression and hinder glycolysis via the IL-6/JAK2/STAT3 signaling pathway." (PMID 41184232, 2025). "In our study, FTO was downregulated in papillary thyroid carcinoma (PTC) tissues." (PMID 35721711, 2022). "Upon combination analysis of meRIP-Seq and RNA-Seq and selection of SLC7A11, it is speculated that SLC7A11 may be used as a downstream target gene of FTO to regulate papillary thyroid carcinoma." (PMID 35721711, 2022). "Therefore, it is worth considering whether m6A also plays a pivotal role in modulating the progression of papillary thyroid carcinoma, yet studies on the role of demethylase FTO in oncogenesis of papillary thyroid carcinoma (PTC) remain rare." (PMID 35721711, 2022). "However, dysregulation of m6A modification and effect of m6A demethylase fat-mass and obesity-associated protein (FTO) on glucose metabolism has not been fully elucidated in papillary thyroid cancer (PTC)." (PMID 35090515, 2022). "First, we first verified whether FTO altered the m6A levels in papillary thyroid cancer cell lines, and we found that TPC-1-Lv-FTO occurred with the downregulation of m6A levels, while KTC-1-shFTO occurred with the upregulation of m6A levels." (PMID 35721711, 2022).
sarcopenia (13 papers, 2017 to 2025). Progressive decline in muscle mass due to aging which results in decreased functional capacity of muscles. "A previous study on genetic markers for sarcopenia identified the loci near FTO, ESR1, NOS3, KLF5, and HLA-DQA1 to be associated with physical phenotypes, such as low handgrip strength and decreased LBM24–26." (PMID 35241739, 2022). "Several studies have associated single-nucleotide polymorphisms (SNPs) with muscle mass and strength in the elderly, and recently our group found that sarcopenia in elderly women was associated with polymorphisms in FTO, TRHR, ESR1, and NOS3." (PMID 34768452, 2021). "Four SNPs were associated with the %SMM and SMI definitions of sarcopenia; FTO rs9939609, ESR1 rs4870044, NOS3 rs1799983 and TRHR rs7832552." (PMID 32076017, 2020). "The present study identified FTO rs9939609 AA homozygotes to be at over 3-fold higher risk for sarcopenia compared to T-allele carriers." (PMID 32076017, 2020). "It therefore appears that FTO AA-genotype individuals have lower skeletal muscle mass and are at higher risk of sarcopenia." (PMID 32076017, 2020). "We found 29 single nucleotide polymorphisms (SNPs) in FTO significantly associated with sarcopenia (combined p-values ranging from 5.92 × 10−12 to 1.69 × 10−9)." (PMID 32193455, 2020). "It seems then that variation within the FTO gene can modify the risk of both sarcopenia and AD." (PMID 38790190, 2024). "FTO rs9939609 AA homozygotes have been related to the risk for sarcopenia in older women." (PMID 38397196, 2024). "Interestingly, Khanal and colleagues (2020) have shown that the FTO rs9939609 variant seems to be associated with sarcopenia, but the association was dependent on the definition used to describe the condition." (PMID 38790190, 2024). "Thus, the observation made in our study on FTO variant associated with soft lean mass is novel and important in the field of sarcopenia." (PMID 32076432, 2019). "This study analyzed 24 SNPs but found that only 4 SNPs (FTO rs9939609, ESR1 rs4870044, NOS3 rs1799983, and TRHR rs7832552) were significantly associated with sarcopenia." (PMID 40428823, 2025). "Analysis of the enriched biological processes identified via GO analysis of the cohorts revealed that alpha-ketoglutarate-dependent dioxygenase FTO is related to sarcopenia." (PMID 35241739, 2022). "It should be noted that the SNPs showing associations in the present study (ACTN3 rs1815739, MTHFR rs1801131, and MTHFR rs1537516) are different from our previous study that identified associations of FTO, TRHR, ESR1, and NOS3 gene variants with sarcopenia." (PMID 34768452, 2021). "Based on the %SMM definition, the SNPs FTO rs9939609, ESR1 rs4870044 and NOS3 rs1799983 were associated with sarcopenia." (PMID 32076017, 2020). "Moreover, our findings can explain some of the confusing human genetics findings on related FTO SNPs, including with regards to sarcopenia." (PMID 40055326, 2025). "Furthermore, the role of FTO SNPs in sarcopenia has also been demonstrated in COPD patients by Attaway and coworkers using a GWAS design followed up with in vitro FTO knockdown experiments." (PMID 38790190, 2024). "Studies demonstrate that FTO SNPs may also be associated with lean mass index (LMI) and sarcopenia." (PMID 38397196, 2024). "This paradox can be easily understood and resolved based on our H19-IGF2 findings, as young adults display the early phase of growth due to FTO-m6A-H19-IGF2-insulin signaling, whereas the elderly manifest with sarcopenia in the later phase due to excessive insulin signaling and insulin resistance." (PMID 40055326, 2025). "When considering the possible molecular mechanism from FTO via IRX3 to OLIG2 resulting in greater lifelong motor neuron availability, this may have implications for muscle size-related disorders such as sarcopenia and cachexia." (PMID 28103813, 2017).
ischemia (12 papers, 2021 to 2026). A hypoperfusion of the BLOOD through an organ or tissue caused by a PATHOLOGIC CONSTRICTION or obstruction of its BLOOD VESSELS, or an absence of BLOOD CIRCULATION. "In a previous study, expression of FTO was found down-regulated causing an increase in global m6A in the HF due to ischemia compared with the normal heart." (PMID 37583580, 2023). "It is noteworthy that FTO was discovered to be downregulated in failing mammalian hearts, and it exhibited a protective function during ischemia by selectively removing methylation from transcripts associated with cardiac contraction." (PMID 40606020, 2025). "FTO ameliorates ischemia-induced cardiac systolic dysfunction, which is induced by the demethylating effect of FTO, leading to an inhibition of degrading cardiac contractile transcripts and an enhanced expression of transcripts in the ischemic state." (PMID 39157458, 2024). "Further studies revealed that FTO overexpression prevented the degradation of cardiac contractile transcripts and improved their protein expression under ischemia conditions through selective demethylation." (PMID 35628623, 2022). "Overexpressing FTO improved Ca2+ amplitude, arcomere dynamics, and contractile function in hypoxia-treated cardiomyocytes in vitro, and myocardial delivery of FTO attenuated ischemia-induced cardiac dysfunction in failing mice hearts in vivo." (PMID 35571209, 2022). "Both sustained and transient overexpression of FTO attenuated ischemia-induced cardiac dysfunction in mouse models of myocardial infarction." (PMID 35628623, 2022). "A recent study reported that FTO is downregulated in failing human and mouse hearts, and FTO plays a protective role under ischemia by selectively demethylating cardiac contractile transcripts." (PMID 34413770, 2021). "Thus, upregulation of FTO could improve decline of cardiac function and fibrosis in post-ischemia mice by promoting angiogenesis." (PMID 36351918, 2022).
Myocardial fibrosis (12 papers, 2021 to 2025). "Overexpression of FTO reversed the benefits of exercise, leading to enhanced myocyte apoptosis, myocyte hypertrophy, and myocardial fibrosis." (PMID 39756462, 2025). "Following FTO knockout, there is an elevation of myocardial fibrosis genes, oxidative stress factors, and iron overload, exacerbating DOX-induced apoptosis, ROS accumulation, and myocardial fibrosis in mice." (PMID 40001550, 2025). "In line with the association between m6A levels and myocardial fibrosis, multiple studies have also reported the involvement of the m6A demethylase FTO in the attenuation of myocardial fibrosis." (PMID 39756462, 2025). "Recent studies have shown that FTO plays an essential role in the progression of myocardial fibrosis." (PMID 37238719, 2023). "In a MI mouse model, FTO overexpression can reduce myocardial fibrosis, enhance angiogenesis, and improve cardiac function." (PMID 35858921, 2022). "A study demonstrated that in the diabetic heart disease mice model, FTO was downregulated in the heart tissue, and the overexpression of FTO improved the cardiac function by reducing myocardial fibrosis and myocyte hypertrophy in db/db mice." (PMID 36157472, 2022). "Taken together, these data indicate that reconstitution of FTO prevented myocardial fibrosis and myocyte hypertrophy, and overexpression of FTO improved cardiac systolic and diastolic function in db/db mice." (PMID 34368154, 2021). "In summary, overexpression of FTO improves cardiac function by reducing myocardial fibrosis and myocyte hypertrophy." (PMID 34368154, 2021). "Overexpression of FTO in DCM model mice improved cardiac function by reducing myocardial fibrosis and myocyte hypertrophy." (PMID 34368154, 2021). "Eight weeks after adenovirus injection, reconstitution of FTO efficiently prevented myocardial fibrosis by reducing interstitial fibrosis in db/db mouse hearts." (PMID 34368154, 2021). "Overexpression of FTO significantly improved cardiac function by reducing myocardial fibrosis and myocyte hypertrophy in db/db mice." (PMID 34368154, 2021). "FTO is downregulated in DCM, and overexpression of FTO improves cardiac function by reducing myocardial fibrosis and myocyte hypertrophy." (PMID 34368154, 2021). "FTO is downregulated in db/db mice compared with db/ + mice, and overexpression of FTO in db/db mice improved cardiac function and significantly reduced myocardial fibrosis and myocyte hypertrophy." (PMID 34368154, 2021). "Moreover, treadmill training in mice with HF with preserved ejection fraction (HFpEF) results in higher total m6A levels, downregulation of FTO protein levels, inhibition of myocardial cell apoptosis, myocardial fibrosis, and myocardial hypertrophy." (PMID 40001550, 2025). "However, overexpression of FTO counteracts the beneficial effects of exercise in HFpEF mice by inducing myocyte apoptosis, myocardial fibrosis, and myocyte hypertrophy." (PMID 37815911, 2024). "FTO has been reported to promote angiogenesis and reduce myocardial fibrosis after myocardial ischemia, however, in the brain, it is predominantly expressed in neurons, whereas downregulation of FTO and ALKBH5 after stroke can induce secondary brain injury by destroying neurons." (PMID 35747214, 2022). "In our study, overexpression of FTO also reduced myocardial fibrosis." (PMID 34368154, 2021). "This highlights FTO’s protective mechanism in the heart, where selective demethylation of myocardial contractile transcripts under ischemic conditions enhances mRNA stability and protein expression, ultimately reducing myocardial fibrosis and promoting angiogenesis." (PMID 39192357, 2024).